OPN3 (opsin 3)
Description:
G protein-coupled photoreceptor that selectively activates G(i/o) proteins in response to light, thereby decreasing intracellular cAMP levels. Activation occurs when the opsin-bound cis-retinal chromophore absorbs a photon and isomerizes to all-trans-retinal, inducing a conformational change in the opsin that triggers a G protein-mediated phototransduction cascade. Mediates blue light-induced pigmentation in melanocytes by activating calcium/CAMK2 signaling, followed by phosphorylation of CREB, p38, ERK and MITF. Required for TYR and DCT blue light-induced complex formation in melanocytes. Involved in keratinocyte differentiation in response to blue-light. Plays a role in melanocyte survival through regulation of intracellular calcium levels and subsequent BCL2/RAF1 signaling. Additionally, regulates apoptosis via cytochrome c release and subsequent activation of the caspase cascade. Responsible for ultraviolet A (UVA)- induced keratinocytes supranuclear melanin cap formation via activating calcium/CAMK2, CREB, and Akt signal transduction, and ultimately increasing DYNC1I1 and DCTN1 expression levels, thereby playing a role in the skin response to UV radiation. Required for the UVA-mediated induction of calcium and MAPK signaling resulting in the expression of MMP1, MMP2, MMP3, MMP9 and TIMP1 in dermal fibroblasts. Also plays a role in light-mediated glucose uptake, mitochondrial respiration and fatty acid metabolism in brown adipocyte tissues. May be involved in photorelaxation of airway smooth muscle cells, via blue light-dependent GPCR signaling pathways (By similarity). Also inhibits melanogenesis in melanocytes by specifically inhibiting MC1R-evoked cAMP signaling in a constitutive, light-independent manner. In the paraventricular nucleus of the hypothalamus, inhibits MC4R-mediated cAMP signaling and activates KCNJ13 channel opening in a constitutive manner, thereby promoting food intake and modulating spontaneous firing of neurons.
Synonyms: ECPN; ERO; NMO-1; encephalopsin; PPP1R116
Tractability: Small molecule: it belongs to a druggable protein family. Antibody: UniProt places it where antibodies can reach, with high confidence; its Gene Ontology location is reachable by antibodies, with high confidence; UniProt predicts a signal peptide or a membrane-spanning region. PROTAC: ubiquitination databases record sites on it.
Target class: Opsin; Membrane receptor; Family A G protein-coupled receptor
Gene: Protein-coding gene on chromosome 1 (241,590,102 to 241,677,376, reverse strand). Ensembl gene ENSG00000054277.
Subcellular location: Cell membrane; Cytoplasm
Subcellular location (Human Protein Atlas): Cytosol; Nucleoplasm; Basal body; Plasma membrane; Primary cilium
Pathways (Reactome):
Signal Transduction: G alpha (i) signalling events; Opsins
Gene Ontology:
Molecular function: 11-cis retinal binding; all-trans retinal binding; G protein-coupled photoreceptor activity; G protein-coupled receptor activity; protein binding; photoreceptor activity
Biological process: adenylate cyclase-inhibiting G protein-coupled receptor signaling pathway; cellular response to UV-A; keratinocyte differentiation; melanosome localization; negative regulation of apoptotic process; negative regulation of melanin biosynthetic process; positive regulation of melanin biosynthetic process; response to blue light; cellular response to light stimulus; detection of light stimulus; G protein-coupled receptor signaling pathway; phototransduction; positive regulation of eating behavior; regulation of circadian rhythm; detection of visible light; positive regulation of cellular respiration; positive regulation of D-glucose import
Cellular component: cytoplasm; cytosol; plasma membrane; membrane; photoreceptor outer segment
Genetic constraint (gnomAD): Loss-of-function variants: 29 observed, 34.06 expected, observed/expected ratio (o/e) 0.85, 90% interval 0.63 to 1.16. The upper end of that interval is the gene's LOEUF score, 1.16, which puts it in group 5 of 6, group 1 being the genes least tolerant of losing a copy. Missense variants: 437 observed, 508.59 expected, observed/expected ratio (o/e) 0.86, 90% interval 0.79 to 0.93. Synonymous variants: 216 observed, 206.35 expected, observed/expected ratio (o/e) 1.05, 90% interval 0.94 to 1.17.
Homologues: Orthologues: chimpanzee OPN3 (99% identical), macaque OPN3 (99% identical), dog OPN3 (92% identical), guinea pig OPN3 (88% identical), rat Opn3 (88% identical), mouse Opn3 (87% identical), rabbit OPN3 (77% identical), zebrafish opn3 (58% identical), Drosophila melanogaster ninaE (21% identical), Drosophila melanogaster Rh2 (21% identical), Drosophila melanogaster Rh3 (17% identical), Drosophila melanogaster Rh4 (17% identical), and 1 more. Paralogues in human: RHO (24% identical), OPN1LW (24% identical), OPN1MW (23% identical), OPN1MW2 (23% identical), OPN1MW3 (23% identical), OPN4 (23% identical), RRH (23% identical), OPN1SW (22% identical), OPN5 (21% identical).
Diseases named in the same sentence as OPN3 in open-access papers:
OPN3 is named in the same sentence as 45 diseases in open-access papers, as found by Europe PMC text mining. Sharing a sentence is not in itself a finding about the gene and the disease. The quoted sentences say what the papers report.
lung adenocarcinoma (8 papers, 2020 to 2024). A carcinoma that arises from the lung and is characterized by the presence of malignant glandular epithelial cells. "In human tumours, previous studies showed that the OPN3 gene was upregulated in lung adenocarcinoma and skin melanoma, which was associated with the metastatic phenotype and unfavourable prognosis." (PMID 35180853, 2022). "For OPN3, its high expression was associated with a lower survival rate in lung adenocarcinoma and acral melanoma." (PMID 35463319, 2022). "For lung cancers, overexpression of OPN3 was shown to promote epithelial-mesenchymal transition and metastasis in lung adenocarcinoma." (PMID 35180853, 2022). "With the increase in OPN3 expression, the mortality rate of lung adenocarcinoma patients increases, and the survival time decreases." (PMID 34630524, 2021). "It has been reported that the OPN3 gene enhances the metastasis of lung adenocarcinoma, and its overexpression promotes epithelial-mesenchymal transition." (PMID 34630524, 2021). "Our study demonstrated for the first time that OPN3 gene enhanced the metastasis in lung adenocarcinoma, and its overexpression promoted epithelial‐mesenchymal transition." (PMID 31802643, 2020). "A significant finding of the study was that OPN3 acted an oncogene in promoting lung adenocarcinoma metastasis." (PMID 31802643, 2020). "OPN3 can be used as a prognostic biomarker for lung adenocarcinoma." (PMID 34630524, 2021). "In tumors, recently reports showed that OPN3 gene was upregulated in pulmonary carcinoid tumors that developed postsurgical metastasis, and OPN3 promoted the epithelial‐mesenchymal transition and metastasis in lung adenocarcinoma." (PMID 33955704, 2021). "Our study complemented the research on the expression and function of OPN3 in lung adenocarcinoma." (PMID 31802643, 2020). "However, the expression and role of OPN3 in lung adenocarcinoma remains unclear." (PMID 31802643, 2020). "The impact of OPN3 or OPN4 on tumor cell activities, such as drug sensitivity, growth, and metastasis, has been reported in hepatocellular carcinoma, colon cancer, and lung adenocarcinoma, and blue light (465 nm) exposure suppresses tumor growth by inducing autophagy." (PMID 34682694, 2021).
hepatocellular carcinoma (7 papers, 2018 to 2022). A malignant tumor that arises from hepatocytes. "Moreover, a previous study revealed that OPN3 was associated with 5-fluorouracil resistance in hepatocellular carcinoma cells, as its depletion activated the antiapoptotic pathway and ultimately influenced hepatocellular carcinoma sensitivity to chemotherapy." (PMID 35180853, 2022). "Three recent studies have reported that OPN family member 3 (OPN3) can induce cell apoptosis in melanocytes and hepatocellular carcinoma." (PMID 35445026, 2022). "Expression level of opn3 has been negatively correlated with the activity of anti‐apoptotic pathway in hepatocellular carcinoma." (PMID 33987975, 2021). "Opsin3 (OPN3), a member of the guanine nucleotide‐binding protein‐coupled receptor superfamily, has been identified to affect the apoptosis of hepatoma cells by modulating the phosphorylation of Akt and Bcl2/Bax." (PMID 31802643, 2020). "Although no direct links between OPN3 and 5FU treatment have been identified in normal cells, in hepatocellular carcinoma cells, OPN3 is involved in regulating 5FU-induced apoptosis via control of the phospho-Akt/total Akt and Bcl2/Bax ratios." (PMID 29950993, 2018).
colon cancer (5 papers, 2018 to 2024). "We examined Opn3 mRNA expression levels in TAMs generated by culturing M0 macrophages with the CM of HCT-116 colon cancer cells, which were then exposed to LED or left untreated." (PMID 38822331, 2024). "Based on these results, we conclude that blue LED irradiation induces autophagy and suppresses the growth of colon cancer cells by the Opn3 photoreceptor pathway, which regulates the Gi/o G‐protein α‐subunit." (PMID 29863164, 2018). "The aim of the present study was to investigate the effects of LED on colon cancer cell lines and the role of photoreceptor Opsin 3 (Opn3) on LED irradiation in vitro." (PMID 29863164, 2018). "In our case, Opn3 expression was observed in human colon cancer cells and normal colon tissue was weakly positive for Opn3." (PMID 29863164, 2018). "Furthermore, we revealed that the blue photoreceptor Opsin3 (Opn3), which is expressed in colon cancer cells, can promote the cytotoxic effects of blue light." (PMID 38822331, 2024). "One report indicates that Opn3 acts as a photoreceptor in malignant melanocytes and contributes to phototherapy, and our findings indicate that Opn3 is a potential target for phototherapy as a photoreceptor in colon cancer cells." (PMID 38822331, 2024). "OPN3 has previously been shown to function as a photoreceptor in human colon cancer cells." (PMID 34975518, 2021). "In addition, immunohistochemistry showed that Opn3 protein was highly expressed in tumor tissue of colon cancer compared to non‐tumor tissue." (PMID 29863164, 2018). "The aim of the present study was to investigate the effects of blue LED irradiation on colon cancer cells and to further dissect whether Opn3 functions as a photoreceptor in this process." (PMID 29863164, 2018). "Blue LED irradiation suppressed the growth of colon cancer cells and Opn3 may play an important role as a photoreceptor." (PMID 29863164, 2018). "In this study, human colon cancer cell lines also expressed Opn3 and, from the fact that blue LED's effect was inhibited by Opn3 knockdown or inhibiting the Gi/o G‐protein α‐subunit, Opn3 may play an important role as a G protein‐coupled photoreceptor by cAMP signaling in inducing autophagy." (PMID 29863164, 2018).
lung carcinoma (4 papers, 2012 to 2022). "Considering that OPN3 expression and its association with clinicopathological features and prognosis in lung cancer and melanoma have been reported, in the next section, the characteristics of OPN3 among the other five cancer types are the primary focus." (PMID 35180853, 2022). "OPN3 upregulation associated with metastasis was recently described in two subtypes of lung cancers." (PMID 33955704, 2021). "Notably, it has been found that functional links between OPN3 and tumorigenesis of lung cancer, skin melanoma and clinical prognosis." (PMID 35180853, 2022). "Consequently, our results are consistent with those found in OPN3 expression of lung cancers, and indicate that OPN3 might be a key molecule regulating metastasis of ALMs." (PMID 33955704, 2021).
liver cancer (3 papers, 2021 to 2022). An epithelial or non-epithelial malignant neoplasm that arises from the liver. "Additionally, another light-independent function of OPN3 was that its depletion triggered 5-fluorouracil resistance in liver cancer cells via the antiapoptotic pathway." (PMID 35180853, 2022). "In addition, OPN3 can also sensitize liver cancer cells to 5-fluorouracil treatment by regulating the apoptosis pathway." (PMID 34630524, 2021).
melanoma (3 papers, 2021 to 2023). A malignant, usually aggressive tumor composed of atypical, neoplastic melanocytes. "Also, Cox regression models showed that high OPN3 scores were associated with worse melanoma survival." (PMID 33955704, 2021). "Therefore, it is important that future studies completely elucidate the molecular basis of association between OPN3 and melanoma." (PMID 33955704, 2021). "Furthermore, the analysis of OPN3 gene alterations showed that the frequency of gene mutations was only 0.5% and mainly occurred in cutaneous squamous cell carcinoma, basal cell carcinoma and melanoma." (PMID 35180853, 2022). "We also observed that the upregulation of OPN3 expression promoted the invasion of MV3 melanoma cells in vitro by transwell invasion assay (unpublished data)." (PMID 33955704, 2021). "Additionally, melanoma patients carrying higher expression of OPN3 have shorter overall survival and occurrence of ulceration." (PMID 36597133, 2023). "Of note, OPN3 may serve as the target for therapy of melanoma in future." (PMID 33955704, 2021).
myopia (3 papers, 2024 to 2026). "Recently, non-visual opsins (OPN3, OPN4, and OPN5) have emerged as potentially impacting myopia regulation." (PMID 41620773, 2026).
Obesity (3 papers, 2020 to 2021). Accumulation of substantial excess body fat. "The direct exposure of brown adipose tissues to white light (465 + 565 nm) increased thermogenic capacity in an OPN3-dependent manner, suggesting the potential of phototherapy for obesity and obesity-associated metabolic disorders." (PMID 34682694, 2021). "In this study, we found that Opn3-knockout (Opn3-KO) mice were prone to diet-induced obesity and insulin resistance." (PMID 32040503, 2020). "Thus, Opn3-KO mice were prone to diet-induced obesity and insulin resistance." (PMID 32040503, 2020).
acral lentiginous melanoma (2 papers, 2021 to 2022). A form of melanoma occurring most often on the plantar, palmar, subungual, and periungual skin. "We have detected the expression characteristic of OPN3 in acral lentiginous melanomas, and demonstrated that high OPN3 is a negative prognostic indicator." (PMID 33955704, 2021).
asthma (2 papers, 2009 to 2020). "Interestingly, OPN3 has light‐independent roles in the asthma and cell cycle modulation of hair follicle cells." (PMID 31730232, 2020). "OPN3 also plays light‐independent roles in asthma and cell cycle modulation of hair follicle cells." (PMID 31730232, 2020).
breast carcinoma (2 papers, 2007 to 2020). "A number of GPCRs have been previously reported to be overexpressed in breast cancer, including CCR1, Opsin-3, CXCR4, PAR1, PAR2, EP2, EP4, GPR30 and the C3A anaphylatoxin chemotactic receptor, although whether any of these are regulated by RGS2 remains unknown." (PMID 18067675, 2007).
cervical cancer (2 papers, 2020 to 2021). A primary or metastatic malignant neoplasm involving the cervix. "The expression levels of FNDC3A, VEGFA, OPN3 and CPE were all high in cervical cancer tissues." (PMID 34630524, 2021).
Hypodontia (2 papers, 2022 to 2023). The absence of five or less teeth from the normal series by a failure to develop. "Earlier, traditional research on non-syndromic hypodontia focused on finding variants in candidate genes, but current trends using WES have revealed new mutated genes for non-syndromic hypodontia, including OPN3, which was previously thought to be irrelevant to tooth development." (PMID 37745851, 2023).
lung carcinoids (2 papers, 2021). "In lung carcinoids, patients with high OPN3 expression are more likely to experience relapse and metastasis." (PMID 34630524, 2021).
skin cancer (2 papers, 2022 to 2023). "Furthermore, OPN3 gene alterations were analysed in 8 different pancancer and 19 skin cancer datasets from the cBioPortal database." (PMID 35180853, 2022).
Anxiety (1 paper, 2022). Intense feelings of nervousness, tension, or panic often arise in response to interpersonal stresses. "Opn3-deficient mice perform comparably to wild-type mice in measures of motor coordination, socialization, anxiety-like behavior, and various aspects of learning and memory." (PMID 36041828, 2022).
behavioral disorders (1 paper, 2021). "Other Opn3-eGFP+ subthalamic structures that are related to the basal ganglia, and involved in modulated motor control, include the white and gray matters of the fields of Forel, a structure implicated in epilepsy, movement and behavioral disorders, as well as the subthalamic nucleus." (PMID 34417283, 2021).
colorectal cancer (1 paper, 2024). A primary or metastatic malignant neoplasm that affects the colon or rectum. "The major limitations of this study are that experiments using mouse colorectal cancer cells and mouse macrophages were not conducted and that the significance of OPN3 expression in tumors and macrophages has not been fully investigated." (PMID 38822331, 2024).
COVID-19 (1 paper, 2021). A disease caused by infection with severe acute respiratory syndrome coronavirus 2. "The expression of OPN3 and OPN4 in airway smooth muscle also suggested the impact of blue light exposure on vasorelaxation for the treatment of pulmonary disorders caused by COVID-19." (PMID 34682694, 2021).
glioma (1 paper, 2022). A benign or malignant brain and spinal cord tumor that arises from glial cells (astrocytes, oligodendrocytes, ependymal cells). "Together, these results suggested that the upregulation of OPN3 expression was associated with clinicopathological features and poor disease outcome of glioma." (PMID 35180853, 2022). "In addition, OPN3 expression in grade II-IV gliomas with IDH mutation or 1p19q deletion was lower in the CGGA dataset than in IDH wild-type gliomas (p < 0.005)." (PMID 35180853, 2022). "In contrast to LGG, the OPN3 gene was expressed at a higher level in GBM, which was consistent with the expression trend of OPN3 protein levels increasing gradually from grade II (LGG) to IV (GBM) glioma." (PMID 35180853, 2022). "Therefore, the gene expression difference of OPN3 was compared between gliomas of different grades using the CGGA dataset." (PMID 35180853, 2022). "In contrast to grade I glioma and LGG, OPN3 was expressed at a higher level in GBM (p < 0.0001 and p = 0.001, respectively)." (PMID 35180853, 2022). "As we showed above, at the glioma RNA level, OPN3 appeared to be downregulated in LGG and GBM compared to normal tissues." (PMID 35180853, 2022). "Additionally, the verification of OPN3 protein levels was not able to fulfil the lack of normal tissues as controls in glioma." (PMID 35180853, 2022).
lymph node metastasis (1 paper, 2020). "The LUAD patients with high expression of OPN3 had poor survival and were more prone to lymph node metastasis." (PMID 31802643, 2020). "The clinicopathological data showed that the expression of OPN3 was correlated with the lymph node metastasis in LUAD patients." (PMID 31802643, 2020). "Analysis of TCGA data revealed the same trend of OPN3 being negatively correlated with OS and DFS and directly correlated with lymph node metastasis in LUAD patients." (PMID 31802643, 2020).
melasma (1 paper, 2021). "To date, the differential expression of OPN3 in melasma skin compared to adjacent skin has not been investigated." (PMID 33812749, 2021). "The results of this study suggest that the expression of OPN3 does not justify the difference in skin pigmentation in melasma in comparison with the unaffected adjacent skin." (PMID 33812749, 2021). "In conclusion, there is no differential expression of OPN3 in keratinocytes, melanocytes, or fibroblasts in facial melasma when compared to the unaffected adjacent skin." (PMID 33812749, 2021).